CD4 (CD4 molecule)
Diseases named in the same sentence as CD4 in open-access papers (continued):
Sharing a sentence is not in itself a finding about the gene and the disease.
lymphopenia (continued). "For CHIKV, productive monocyte infection occurs and, in patients, very early CD95/Fas-mediated apoptosis of CD4 T cells accompanies marked lymphopenia; CHIKV also engages intrinsic/extrinsic apoptotic programs with potential bystander effects." (PMID 41346606, 2025). "This pattern appears to differ from the typical lymphopenia described in sepsis, where both CD4+ and CD8+ T cells are often depleted in similar proportions." (PMID 40740787, 2025). "The severe CD4+ lymphopenia in our HIV-infected patient further highlights the importance of screening for secondary immunodeficiencies." (PMID 40656199, 2025). "The lymphopenia was reflected in the stable, reduced numbers of both CD4+ and CD8+ T cells, unaffected by diabetes development in the BBM Gimap5-DP rats." (PMID 41042382, 2025). "In patients with septic shock and lymphopenia, CYT107 caused a 3- to 4-fold increase in circulating CD4 and CD8 T cells as well as inducing T cell proliferation and activation." (PMID 39903535, 2025). "Similar to our study, they found that at 2 years after KTx, 27% had CD4 T cell lymphopenia (< 300 cells/ul) and that this cutoff increased mortality (24.1% vs 7.6%, HR 4.63)." (PMID 40612959, 2025). "In a cohort of 60 adult patients with cirrhosis T CD4+ lymphopenia was observed, attributing it to defective lymphocyte production, splenic pooling and apoptosis from bacterial translocation." (PMID 40574851, 2025). "Idiopathic CD4+ lymphopenia, a rare condition with an estimated prevalence of 0.02–0.05%, was confirmed in two patients and suspected in a third, suggesting a higher-than-expected frequency." (PMID 40558973, 2025). "A consistent immunological finding was persistent lymphopenia with markedly low CD4+ T-cell counts (median 167 cells/μL)." (PMID 41179870, 2025). "Immunological workup at 18 years of age showed CD4+ and CD8+ T-cell lymphopenia, and genetic analysis revealed a homozygous pathogenic ZAP70 splice-site mutation (c.402 + 2 T>C)." (PMID 40901120, 2025). "By PV10d, NTV mice exhibited significant splenic lymphopenia: CD4+ and CD8a+ T cell frequencies decreased 48% and 37% versus CON (P < 0.01), respectively, with concomitant reduction in CD4+/CD8a+ ratios." (PMID 40709179, 2025). "In clinical trials of patients with HIV infection who had lymphopenia despite optimal antiretroviral therapy, CYT107 caused a 2- to 4-fold dose-dependent increase in circulating CD4 and CD8 T cells." (PMID 39903535, 2025). "Lymphopenia, characterized by a reduction in lymphocyte counts, is commonly observed in sepsis, with a significant depletion of CD4+ T cells." (PMID 40642098, 2025). "The key signal factors IFN-γ (Ifng), IL17a (formally regarded as IL-17), and IL21 were detected by ELISA to assess the influence of activation and lymphopenia of the CD4+ T cells on the inflammatory state." (PMID 40756359, 2025). "Analysis of lymphocyte subsets revealed CD3+ T-cell lymphopenia in 18.6% of patients, with CD4+ lymphopenia in 27.9%, although naïve CD4+ T-cell counts were consistently normal in all tested patients." (PMID 40692796, 2025). "The resultant lymphopenia impacts several critical lymphocyte subtypes, including T helper cells (Th cells CD4+), cytotoxic T cells (Tc cells CD8+), B lymphocytes, and natural killer T cells CD3+ (NKT)." (PMID 40005375, 2025). "CMV retinitis is an emerging and serious complication after auto-HCT, strongly correlated with prolonged immunosuppression–particularly from T-cell-depleting monoclonal antibodies and corticosteroids–resulting in sustained CD4+ T lymphopenia." (PMID 41179870, 2025). "We show in a more contemporary population that lymphopenia at 3 years involves not only CD4+ T cells, but also almost all T cell types, B cells and NK cells." (PMID 40612959, 2025). "The simulation demonstrated a predictable increase in viral load and epithelium damage, resulting from the development CD4+ T cell lymphopenia, which affects both cellular and humoral immune responses." (PMID 40431602, 2025).
lymphopenia (continued). "Results were consistent with the known immunologic alterations occurring in HDP cohorts related to lymphopenia, chronic inflammation, and dysregulated proliferation of CD4+." (PMID 40370459, 2025). "Other studies have reported that patients with COVID‐19 exhibit lymphopenia accompanied by a significant reduction in T‐cell subsets, with CD4+ and CD8+ T‐cell numbers progressively declining as the disease advances." (PMID 41146434, 2025). "Laboratory workup showed CD4 lymphopenia, normal IgG and IgA, low IgM at < 10 mg/dL, and high IgE at 2916 mg/dL." (PMID 41222818, 2025). "Despite stopping MMF and tapering prednisolone, along with immune disease control using IVIG, lymphopenia continued, although the CD4+ T cell count increased to 153/μL." (PMID 41583153, 2025). "Analysis of lymphocyte subpopulations showed lymphopenia of T CD4+, B, and NK cells, with an increase in T CD8+ lymphocytes." (PMID 40756102, 2025). "The immunological phenotype was consistent and highly suggestive of this diagnosis, showing markedly reduced HLA-DR expression, profound CD4+ T-cell lymphopenia, and impaired immunoglobulin production." (PMID 41376631, 2025). "Flow cytometry revealed CD4+ T-cell lymphopenia (555 cells/mm3), an expansion of CD8+ T cells (2430 cells/mm3), and an inverted CD4/CD8 ratio (0.23)." (PMID 41376631, 2025). "At that moment peripheral blood showed a normal absolute T cell count (2568cells/uL) with CD4 + T cell lymphopenia (556cells/uL) and an inverted CD4/CD8 ratio (0.3), absolute B cells were low (70.9cells/uL 2,3%) and NK cells were normal (183cells/uL)." (PMID 41472689, 2025). "CD4+ lymphopenia was present in 33.3% of Q257R patients and 20.0% of Y130C patients, with the majority of patients in both groups maintaining normal CD8+ T-cell levels." (PMID 40692796, 2025). "Because an idiopathic CD4+ lymphopenia diagnosis is often retrospective, a comprehensive immunological work-up and longitudinal follow-up are essential." (PMID 40558973, 2025). "In investigations of the patient, besides lymphopenia, IgG and its subgroups and IgA were low, and the CD4/CD8 ratio was reversed." (PMID 41399590, 2025). "The sepsis characterized by leukocytosis shows a significant increase in neutrophils and monocytes, followed by the state of lymphopenia including B cells, CD4 T cells, and CD8 T cells." (PMID 40821971, 2025). "Laboratory evaluation revealed profound lymphopenia (270/μL) with a CD4+ T-cell count of 58/μL and an inverted CD4/CD8 ratio." (PMID 41583153, 2025). "The patient had CD4+ lymphopenia, with a marked reduction of naïve CD4+ T cells, and impaired T cell proliferation to specific antigens." (PMID 40977713, 2025). "The long-acting interleukin-7 NT-I7 is safe and increases absolute lymphocyte counts and CD4 T-cell counts in patients with newly diagnosed high-grade gliomas with severe treatment-related CD4 lymphopenia." (PMID 40703805, 2025). "In our case, the immunological profile, featuring CD4+ lymphopenia and elevated IgE, corresponds to previously reported “hyper-IgE–like” phenotypes occasionally observed in TYK2 deficiency." (PMID 41465118, 2025). "Lymphocyte population studies revealed CD4 lymphopenia, when compared to age-matched reference values, with a low expression of HLA class II on B lymphocyte (2.4%), confirming the diagnosis of MHC-II deficiency." (PMID 40756102, 2025). "This profile — profound CD4 lymphopenia and markedly reduced HLA-DR expression — was highly suggestive of MHC class II deficiency." (PMID 41376631, 2025). "The paradoxical increase in CD4+ helper T-cells, however, contrasts with the CKD-associated CD4+ lymphopenia, which was proposed to be transient margination of memory CD4+ T-cells into lymphoid tissues during HD." (PMID 41010736, 2025). "Patients with higher EULAR Sjögren syndrome disease activity indexes (ESSDAI) were associated with a higher proportion of activated CD4+ and CD8+, and more pronounced CD4+ lymphopenia." (PMID 39896815, 2024).
lymphopenia (continued). "Patients who developed severe CD4+ lymphopenia during standard therapy experienced higher hospitalization and infection rates." (PMID 38390330, 2024). "In an RCT studying intramuscular recombinant human IL-7 (CYT107) in 27 patients with severe lymphopenia, CYT107 reversed the loss of CD4+ and CD8+ cells." (PMID 38807151, 2024). "In contrast, P2, P1’s sister, had a normal count of T, B, and NK cells, with the exception of a mild CD4+ T cells lymphopenia." (PMID 39339890, 2024). "Both the disease severity and CD4+ T-cells depletion were directly correlated with lymphopenia and higher levels of CXCL10 biomarker." (PMID 38965547, 2024). "Individuals with thymic defects due to 22q11.2 deletion syndrome and FOXN1 haploinsufficiency can have a marked T cell lymphopenia early in life with a gradual normalization of CD4+ and CD8+ T cell numbers possibly due to homeostatic expansion." (PMID 39364398, 2024). "Taken together, this study supports the theory that a profound CD4 + T cell and B cell lymphopenia is important for patients with SSc to achieve a sustained response after aHSCT." (PMID 38509633, 2024). "In our study, we observed CD4+ T lymphopenia and increased cytokines in intestine tissues of mice stimulated by SARS-CoV-2 spike." (PMID 38686388, 2024). "Both patients presented with normal total T-lymphocyte counts but extremely elevated CD4:CD8 ratio due to CD8 + lymphopenia, which has normalised following HSCT." (PMID 38598033, 2024). "CD4 T cells and CD79a+ B cells were shown to account for the lymphopenia, while CD4+CD8+ T cells were increased at 7 dpi in domestic pigs, and no T-cell activation was detected in terms of Ki67 and T-bet expression." (PMID 38419627, 2024). "In our comprehensive acute myocarditis cohort, i.e., patients along the full disease spectrum, both CD8+ and CD4+ T cell lymphopenia were more common in those with complicated myocarditis." (PMID 38398340, 2024). "Our recent study also revealed a high incidence of lymphopenia in ATAAD and demonstrated that CD4+ T cell lymphopenia was associated with poor postoperative outcomes in these patients." (PMID 39266539, 2024). "She had lymphopenia (total lymphocyte count 670 cells/mmc, CD4 + T cells 363 cells/mmc, CD8 + T cells 189 cells/mmc, NK cells 91 cells/mmc) and suffered from chronic lung disease characterized by bronchiectasis and frequent bacterial exacerbations." (PMID 38578354, 2024). "Routine immunological workup revealed persistent lymphopenia, with decreased absolute numbers of total T cells as well as of CD4+ and CD8+ T cells." (PMID 39270020, 2024). "Our analysis revealed that the proportions of resting NK cells and naive CD4 T cells were similarly downregulated in both TE high and TE low groups, reflecting the general lymphopenia state observed in SLE patients." (PMID 39427224, 2024). "Three cases from our cohort died because of severe sepsis and only one presented lymphopenia with low T lymphocytes CD4+." (PMID 39336737, 2024). "Our study revealed that concomitant helminth and TB infection was associated with a low CD4, a low CD4/CD8 ratio and lymphopenia." (PMID 39062045, 2024). "With regards to lymphocyte subsets, DKO mice had a profile similar to SHIP-1−/− mice, exhibiting a lymphopenia phenotype with reductions in CD4+ and CD8+ T cells." (PMID 39432107, 2024). "CXCR4 antagonism corrected peripheral blood CD4+ and CD8+ T-cell lymphopenia in these mice and even restored the circulating CD4/CD8 T-cell ratios to WT levels after 7 days and 28 days of treatment." (PMID 39588369, 2024). "The detected CD4 lymphopenia dramatically altered the normal CD4/CD8 ratio in combination with an increase in CD8+ T cells, an increase of which is associated with the presence of long-term inflammation caused by recurrent infections." (PMID 39203969, 2024). "Collectively, our results suggest that the patient’s CD4+ lymphopenia was a result of increased apoptosis." (PMID 39224595, 2024).
lymphopenia (continued). "Our findings show that severe CD4+ T-cell lymphopenia, resulting from advanced SIV infection, significantly impairs the cellular immune response to SARS-CoV-2 in the lungs." (PMID 39066335, 2024). "A previous study found that the absolute lymphocyte subset counts were low in 91% of PD patients, with CD4+ T-cell lymphopenia being the most common." (PMID 38892708, 2024). "The increased apoptotic markers found in patient PBMCs in the presence of idiopathic CD4+ lymphocytopenia suggest that CD4+ T cells are especially sensitive to TRAP1 dysfunction." (PMID 39224595, 2024). "The median lymphocyte count was 846 cells/mm3 (IQR 993), with only two patients presenting severe lymphopenia (13.3%), and the median CD4 count was 348 cell/m3 (IQR 407), with 4/12 patients with counts lower than 100 cell/mm3 (33.3%)." (PMID 39107686, 2024). "Other data suggest that aging, HIV replication and/or HCV infection, and liver cirrhosis each contribute to heightened T-cell activation, leading to naive CD4+ T-cell lymphopenia, another marker of significant morbidity in PWH." (PMID 38192382, 2024). "Peripheral CD4 lymphocytopenia, evoked by lymphocytic sequestration in granulomas and peripheral anergy, have been discussed, but no clear mechanism of virus escape from immune vigilance is yet proposed." (PMID 38256476, 2024). "PJP incidence remains low likely related to widespread use of prophylaxis for a reported 3–6 months starting after neutrophil recovery and/or low rates of sustained CD4 lymphopenia among BCMA CAR-T, though further data is needed." (PMID 39026972, 2024). "CXCR4 antagonism reversed peripheral T-cell lymphopenia and restored the CD4/CD8 T-cell ratio in Cxcr4+/1013 mice." (PMID 39588369, 2024). "This is in line with several studies suggesting poor response and survival in patients with NSCLC and CD4+ lymphopenia." (PMID 38674117, 2024). "We next compared lymphopenia-induced immune responses of MP versus naïve cells by separately transferring MP and naïve Foxp3− CD4+ T lymphocytes into Rag2−/− mice." (PMID 39630890, 2024). "We describe here a patient in his thirties who presented with epidermodysplasia verruciformis (EV) due to infection with a weakly virulent beta-papillomavirus (HPV38) and CD4+ T-cell lymphopenia." (PMID 39110273, 2024). "In terms of the CD4 lymphopenia, the patient had a low CD4 count of 82 cells/μL in June 2020, 9 months after CAR T-cell therapy and before disease relapse, however following initiation of CD20/CD3 BsAb, CD4 T-cell count dropped to a nadir of 5 cells/μL." (PMID 39224237, 2024). "Typically, the suspicion of MHC-II deficiency is raised in patients with recurrent infections, hypogammaglobulinemia, CD4 lymphopenia, and low CD4/CD8 ratio." (PMID 39072316, 2024). "Cellular signature stratified patents into groups with distinct clinical and pathological features.High ESSDAI: more severe CD4 lymphopenia and increase in activated CD4 and CD8." (PMID 39896815, 2024). "This syndrome is defined by the presence of hypogammaglobulinemia, B lymphopenia, CD4 T lymphopenia, abnormal CD4/CD8 ratio, and impaired T cell mitogenic responses associated with recurrent infections, due to encapsulated bacteria, fungi and viruses." (PMID 38898390, 2024). "Although the molecular mechanism remains elusive, a subset of ICF patients exhibit lymphopenia and/or an inverted CD4+/CD8+ ratio due to the reduction of CD4+ T-cells, which potentially hampers activation of naïve B-cells and CSR." (PMID 38799442, 2024). "Future important avenues for investigation include improved infectious disease screening such as CMV surveillance, standardized monitoring of lymphopenias such as serial CD-4 counts, and individualized strategies for PJP prophylaxis in patients with lymphoma." (PMID 39717043, 2024). "Given the prolonged CD4+ lymphopenia risk among PWH undergoing HSCT, primary prophylaxis remains indicated for those with persistently low CD4+ cell counts to prevent MAC." (PMID 39459894, 2024).
lymphopenia (continued). "Our findings also confirm the presence of lymphopenia, particularly in the CD4 + and CD8+ subsets, described by other studies." (PMID 39595989, 2024). "Lymphocytopenia is one of the independent risk factors for RP-ILD in MDA5-positive DM-ILD patients, especially the reduction of CD3 + T cells, CD3 + CD4 + T cells, and CD3 + CD8 + T cells." (PMID 39292419, 2024). "In these diseases, CD4+ T-cell lymphopenia and increased CD8+ T-cell proportions are commonly reported accounting for the demonstration of reverted CD4:CD8 ratios." (PMID 39679264, 2024). "Lymphopenia was observed in 8/15 patients (mild = 3, moderate = 4, severe = 1), and low CD4 counts were observed in 9/12 patients, with less than 100 cells/mm3 in 4 patients." (PMID 39107686, 2024). "In this published case series, CD4+ T cell lymphopenia was less pronounced beyond 2 y of age, while CD8+ counts remained below the normal range in most infants." (PMID 39008056, 2024). "The most common immunophenotypic features were CD4 lymphopenia (78.4%), inverted CD4/CD8 ratio (64.7%), and reduced naïve CD4 (84.4%) and CD8 (87.8%) T cells." (PMID 39072316, 2024). "The immune phenotype seems restricted to the lymphoid lineage with mainly a CD4 lymphopenia originating from a diminution in naïve cell numbers and an increase in the memory compartment." (PMID 39270020, 2024). "Although lymphopenia cannot be directly assumed for all patients with low CD4 counts and vice versa, it appears that those cell count numbers normalized within the time frame of 1–4 months for a considerable proportion of patients." (PMID 38767518, 2024). "Pretransplantation blood immunophenotyping showed also in this case CD4+ and CD8+ T cell lymphopenia and an inversion in the CD4+/CD8+ T cell ratio." (PMID 39270020, 2024). "Consistent with this study, we also observed that B cells and CD4 T cells were the major populations that contributed to lymphopenia, but why and how ASFV induces B cell and CD4 T cell reduction or death require further investigation." (PMID 38419627, 2024). "During experiments, Il2rg KO, Rag2 KO and Il2rg/Rag2 KO rats showed decreased white blood cells and systemic lymphopenia, with reduced CD4+, CD8+ T cells and CD161+ NK cells." (PMID 39731164, 2024). "In some patients, lymphopenia has been reported to involve CD4+ T cells, CD8+ T cells, B cells and NK cells." (PMID 39764446, 2024). "Mice in the IgG group showed severe lymphopenia, with a significantly reduced number of CD4+CD8+ DP thymocytes." (PMID 39776911, 2024). "Information from the periphery is only based on case reports, and persistent selected peripheral lymphopenia (CD8 or CD4+ T cells) has been described in a few cases." (PMID 36761741, 2023). "In humans, deficiencies in RASGRP1 can result in a primary immunodeficiency (PID) syndrome, characterized by lymphopenia in CD4 + T cells and the development of Epstein-Barr virus (EBV)-associated B cell lymphoma." (PMID 38057716, 2023). "SARS‐CoV has been shown to significantly decrease CD4+ and CD8+ T cell counts, and MERS‐CoV has been shown to efficiently infect T cells to cause T cell apoptosis leading to lymphopenia." (PMID 37773701, 2023). "Key PIDs associated with a high risk of progressive HPV disease are characterized by defects in NK cell and CD8+ T cell counts as well as CD4+ T cell lymphopenia." (PMID 36960048, 2023). "Here, we report a rare case of disseminated NTM patient with idiopathic CD4 lymphopenia and anti-IFN-γ antibodies." (PMID 36717786, 2023). "CVID patients are also characterized by an inverted CD4/8 T-cell ratio, a relative CD4+ T-cell lymphopenia and markers of T-cell activation and exhaustion, pointing to an underlying T-cell dysregulation." (PMID 37180118, 2023). "Consistently, we reported a reduction in CD4+ T cells and their proliferative activity at T0, compared to healthy volunteers, and confirmed the lymphopenia occurring during HD (pp." (PMID 37176548, 2023).